TIGD7 (tigger transposable element derived 7)
Synonyms: Sancho
Tractability: Antibody: the Human Protein Atlas places it where antibodies can reach.
Gene: Protein-coding gene on chromosome 16 (3,298,390 to 3,305,729, reverse strand). Ensembl gene ENSG00000140993.
Subcellular location: Nucleus
Subcellular location (Human Protein Atlas): Cytosol; Plasma membrane
Gene Ontology:
Molecular function: protein binding; DNA binding; nucleic acid binding
Cellular component: cytosol; plasma membrane; nucleus
Genetic constraint (gnomAD): Loss-of-function variants: 31 observed, 32.48 expected, observed/expected ratio (o/e) 0.95, 90% interval 0.72 to 1.29. The upper end of that interval is the gene's LOEUF score, 1.29, which puts it in group 5 of 6, group 1 being the genes least tolerant of losing a copy. Missense variants: 663 observed, 623.77 expected, observed/expected ratio (o/e) 1.06, 90% interval 1 to 1.13. Synonymous variants: 216 observed, 218.92 expected, observed/expected ratio (o/e) 0.99, 90% interval 0.88 to 1.1.
Homologues: Orthologues: chimpanzee TIGD7 (99% identical), macaque TIGD7 (98% identical), pig TIGD7 (90% identical), dog TIGD7 (89% identical). Paralogues in human: JRKL (28% identical), JRK (27% identical), TIGD2 (27% identical), TIGD1 (26% identical), TIGD6 (24% identical), TIGD5 (23% identical), TIGD4 (21% identical), CENPB (19% identical), TIGD3 (16% identical), POGZ (14% identical), POGK (13% identical).
Diseases named in the same sentence as TIGD7 in open-access papers:
TIGD7 is named in the same sentence as 5 diseases in open-access papers, as found by Europe PMC text mining. Sharing a sentence is not in itself a finding about the gene and the disease. The quoted sentences say what the papers report.
epilepsy (1 paper, 2012). A brain disorder characterized by episodes of abnormally increased neuronal discharge resulting in transient episodes of sensory or motor neurological dysfunction, or psychic dysfunction. "Although TIGD7 and JRKL are both homologs of the Jrk “jerky” gene associated with epilepsy in mice, they do not have known relevance in cancer development." (PMID 22759657, 2012).
TIGD7 also shares sentences with these, for which no sentence is quoted: cancer (2 papers); head and neck cancer (1); non-small and small-cell lung cancers (1); rectal carcinoma (1).